TNF (tumor necrosis factor)
Diseases named in the same sentence as TNF in open-access papers (continued):
Sharing a sentence is not in itself a finding about the gene and the disease.
cancer (continued). "A total of 96 patients were exposed to VDZ, 184 were exposed to anti-TNF, and 183 had no immunosuppressive therapy after a prior cancer diagnosis." (PMID 36983432, 2023). "Regarded as a TGF-β inhibitor, Hesperetin works on the TGF-β1/Smad pathway-mediated ECM progression and restores the upregulation of IL-1β, PTGS2, and MMP-13 induced by TNF-α, reverses the degradation of the ECM, therefore it has promising therapeutic effects on various cancers." (PMID 37560476, 2023). "It regulates the transcriptional activity of hypoxanthine catabolic enzyme xanthine dehydrogenase (XDH) in cancer cells presumably by regulating the mRNA level of XDH transcriptional stimulators IL-6, TNF-α, and IFN-γ, and promotes the catabolism of hypoxanthine." (PMID 37658353, 2023). "Notably, the proinflammatory cytokine tumor necrosis factor-alpha (TNF-α) is a crucial player in the adipose tissue, playing roles in resistance to infections and cancers." (PMID 37927615, 2023). "Tumor necrosis factor (TNF)-related apoptosis inducing ligand (TRAIL) can induce apoptosis in a wide variety of cancer cells, both in vitro and in vivo, importantly without killing any essential normal cells." (PMID 36195672, 2023). "The death rate following cancer diagnosis was 113 deaths among 302 patients with anti-TNF therapy vs. 256 deaths among 586 patients in the non-anti-TNF exposure group." (PMID 36983432, 2023). "A non-inflammatory senescence-associated secretory profile was induced, significantly decreasing inflammatory cytokines and chemokines such as IL-6, IL-8, TNF, RANTES, and MCP-1; this is consistent with the lower incidence of thyroid inflammation and cancer in men." (PMID 37190127, 2023). "The current study identified VEGF-A, TNF-α, CCL2, IL-6, and IFN-γ (CCL2, IL-6, and IFN-γ after Bonferroni correction) as additional plasma biomarkers reflecting cancer presence, in addition to anti-TIF1-γ antibody, among anti-TIF1-γ antibody-positive DM patients." (PMID 36357631, 2023). "The radiation generated heat and triggered the photo thermolysis in the therapeutic myeloid cells, which, in turn, released the non-secreted form of TNFα, known for the cytotoxic effect on cancer cells." (PMID 36854896, 2023). "Additionally, the inflammatory cytokines, including tumor necrosis factor-alpha (TNF-α), IL-1, and IL-8, affect skeletal muscle, leading to cancer cachexia." (PMID 38067295, 2023). "Moreover, CHIR 99021 is a GSK3 kinase inhibitor that can significantly enhance TNF and IFN production, natural cytotoxicity, and antibody-dependent cellular cytotoxicity for effective cancer immunotherapy." (PMID 36532053, 2022). "Fusobacterium nucleatum, as a cancer-promoting biological factor, can be enriched to the lesion through the specific interaction of Fap2 with Gal-GalNAc antigen on the tumor surface, and lead to the expression of MUC2 and TNF-α in cancer cells." (PMID 36081564, 2022). "The combination treatment-induced systemic immune response was evaluated by measuring the secretion of serum proinflammatory cytokines with ELISA assay, including tumor necrosis factor-alpha (TNF-α), interferon-gamma (IFN-γ) and interleukin-6 (IL-6), that play vital roles in anti-cancer immunity." (PMID 35812418, 2022). "Multiple cytokines and chemokines (TNF-α, TGF-β, granulocyte-macrophage colony-stimulating factor (GM-CSF)), as well as transcription factors (AP-1, NF-kB, STAT3, HIF-1α), participate in inflammatory responses during cancer progression." (PMID 36226048, 2022). "Regarding this proposal, many novel studies have approved that some peptide-related drugs such as mifamurtide, tumor necrosis factor-alpha (TNF-α), interferon-γ (INF- γ), and interleukin-2 (IL-2) cure human diseases including cancer and are found to be more effective." (PMID 35223470, 2022).
cancer (continued). "Pro-inflammatory cytokines, such as interferon (INF)-γ or tumor necrosis factor (TNF)-α, induce tryptophan degradation through the kynurenine pathway, and metabolites of this pathway are involved in the pathogenesis of inflammatory diseases and cancer." (PMID 36059949, 2022). "The PTGES3′s protein partner subset is enriched with pathway terms such as “protein processing in endoplasmic reticulum”, “pathways in cancer” (KEGG); “cellular responses to external stimuli”, “aryl hydrocarbon receptor signaling” and “TNF alpha Signaling Pathway” (Reactome)." (PMID 35453789, 2022). "The results indicated that XLLXF may play an anti-TNBC role, mainly through cancer-related pathways, PI3K/Akt signaling pathways, TNF signaling pathways, HIF-1 signaling pathways, MAPK signaling pathways, and VEGF signaling pathways." (PMID 35379271, 2022). "Further, targeting TNF-α with neutralizing antibodies did not prevent body wasting in cancer patients." (PMID 35319749, 2022). "Moreover, within the cytokine network of culture supernatant, TNF-α and IFN-γ can also be produced by CTLs, which can suppress cancer development." (PMID 36005179, 2022). "SHD may treat IS through signaling pathways, including endocrine resistance, estrogen, TNF, and AGEs/RAGE and microRNAs in cancer." (PMID 35097126, 2022). "One mechanism involved in this positive anti-cancer drug interaction is SHetA2 upregulation of CAAT/Enhancer Binding Protein Homologous Protein (CHOP), which leads to increased cell surface expression of the TNFα and TRAIL Death Receptors (DR4 and DR5)." (PMID 35281109, 2022). "Moreover, the literature shows fucoxanthin’s ability to inhibit cytokines and growth factors such as TNF-α and VEGF, which stimulate the activation of downstream signaling pathways such as PI3K/Akt autophagy and pathways of apoptosis in many cancer cell lines." (PMID 36555740, 2022). "Cautious interpretation is needed not to oversimplify the study results as cancer-protective effects of TNF inhibitors." (PMID 35945635, 2022). "Also, it has been verified that activated NK cells secret immunostimulatory cytokines, including TNF-α and IFN-γ, that are needed for apoptosis induction and sensitizing DRs of cancer cells, respectively." (PMID 35721501, 2022). "Furthermore, a retrospective clinical study involving 144 hospitalized patients with cancers showed that simultaneously elevated IL6 and TNFα levels had a nearly 6-fold increase in mortality." (PMID 35859928, 2022). "Research has indicated that up-regulation of the pro-inflammatory cytokines IL-6, TNF-a, and IFN-γ secreted by cancer tissues could prevent the differentiation of pre-adipocytes and cause-altered phenotypes." (PMID 35756650, 2022). "To confirm whether FGFC1 exerts anti-cancer effects via the NF-κB signaling pathway in vivo, we analyzed the expression of p-p65, IL6, and TNF-α in PC9 xenograft tumors." (PMID 35049931, 2022). "Indels in MSI-H cancer formed some shared frameshift peptides that could combine with MHC I and activate CD8+ T cells, producing IFN-γ and tumor necrosis factor-α (TNF-α)." (PMID 36263174, 2022). "looked into nitric oxide (NO) production by CAFs as a mechanism of inhibiting T cell proliferation in cancer, as this has been found to be a mechanism employed by FRCs after sensing T cell secreted IFN-γ and TNF-α to limit their proliferation in the healthy lymph node." (PMID 35479076, 2022). "In addition, accumulating research showed that MDSCs have potent mechanisms to promote cancer growth (via downregulation of IFN-γ and expression of MMP9) and metastasis (via TNFα, TGFβ, CXCL2 and S100A8/9) by establishing an immunotolerant environment." (PMID 35211124, 2022). "Some studies indicated that macrophages exposed to hypoxia/lactate may secrete IL-6, TNF-α, CCL5 and CCL18, which favor glycolysis and boost synthesis of pro-glycogenic factors in TME in some cancers." (PMID 36362348, 2022).
cancer (continued). "In our work, we showed the exposure of calreticulin in a subpopulation of ferroptotic cells shortly before their rupture, as well as ATP, HMGB1, CXCL1, TNF and IFN-β release in the course of a drug- and genetically induced models of ferroptosis in cancer cells." (PMID 35760796, 2022). "As reviewed elsewhere, IL-1, TNFα, and TLR can promote cancer progression through NF-κB or AP-1." (PMID 35626710, 2022). "Macrophages that infiltrate the TME secrete cytokines, such as IL-6, IL-10, TNF-α, and TGF-β, which may enhance cancer cell stemness and EMT." (PMID 35565306, 2022). "The tumor necrosis factor (TNF) family contributes to the modulation of cellular functions involved in cellular differentiation, survival, proliferation, apoptosis, and especially immune functions against cancer cells." (PMID 36505472, 2022). "POSTN enhanced integrin/ERK/NF-κB signaling through an autocrine effect on cancer cells to produce macrophage attracting and mobilizing cytokines including MIP-1β, MCP-1, TNFα and RANTES resulting in increased chemotaxis of THP-1 monocytes and their polarization to M2 macrophages in vitro." (PMID 36550569, 2022). "Meanwhile, homozygous CNV analysis showed that FADD in 22 cancer types, FASLG in 25 cancer types, RIPK1 in 22 cancer types, TLR3 in 15 cancer types, TNF in 23 cancer types, FAS in 15 cancer types, MLKL in 12 cancer types, and RIPK3 in 17 cancer types had homozygous amplifications." (PMID 35748782, 2022). "Meanwhile, TNF exhibits antitumor activity by acting as an anti-angiogenic factor, increasing vascular permeability in tumors, and enhancing the response of HCC to anti-cancer agents." (PMID 36555597, 2022). "The results of KEGG pathway enrichment revealed that the hub targets mainly related to HIF-1 signaling pathway, NOD-like receptor signaling pathway, proteoglycans in cancer, PI3K-Akt signaling pathway, Toll-like receptor signaling pathway, and TNF signaling pathway." (PMID 35722158, 2022). "In the TME, cancer cells induce expression of MHC-II, CD40, CD80, and CD86 on DCs, together with the release of inflammatory cytokines like IL-12, type I IFN, IL-1β, IL-6 and tumor necrosis factor (TNF)." (PMID 35267487, 2022). "The TERT–NF-κB p65 interaction increased a subset of NF-κB-dependent gene expressions such as IL-6 and TNF-α, which are critical for inflammation and cancer progression, suggesting a noncanonical role for TERT in cancer regulation." (PMID 35741087, 2022). "We did not see increased IFNα and TNFα levels in women with high PD-L1 levels in non-cancer controls." (PMID 35053979, 2022). "Interestingly, same EMT-TFs regulate the expression of various secreted mediators such as growth factors (GM-CSF), cytokine (TNF-α), and chemokines (CXCL6/8/11, CCL2, and GRO) in cancer cells." (PMID 36091114, 2022). "Several signaling pathways (e.g., cytokine–cytokine receptor interaction, TNF signaling, IL-17 signaling, FOXO signaling, pathways in cancer, PI3K-Akt signaling and Toll-like receptor signaling) were identified as significantly enriched in all comparison groups." (PMID 35628542, 2022). "Recently, anti-TNFα antibodies have been used in cancer patients but these trials failed to cure their cachexia." (PMID 36078078, 2022). "The tumor necrosis factor-α (TNF-α) and soluble interleukin-2 receptor (SIL-2R) are targeted markers commonly used in the clinic to diagnose and treat malignancies, and the higher the expression levels of serum TNF-α and SIL-2R, the higher the stage of cancer, and vice versa." (PMID 35186243, 2022). "The use of TNFα by NK cells as a molecule with direct cytotoxic capacity against cancer cells is not clear." (PMID 35651603, 2022). "Among these pathways, we identified cancer-related signaling pathways, including the NF-kappa B (NF-κB) signaling pathway, peroxisome proliferator-activated receptor (PPAR) signaling pathway, PI3K-Akt signaling pathway, and TNF signaling pathway." (PMID 33558702, 2022).
cancer (continued). "Additionally, with NIR irradiation, more pDNA was released, making it easier to destroy the DNA of cancer cells, and the photothermal effect of ADP@SWNT/TNFα also inhibited cell proliferation." (PMID 34994069, 2022). "We split the data into two groups according to the median level of KRAS and observed that some important signatures (EMT, apoptosis, and TNFα/NFκB signaling) and immune cell infiltration were inclusively enriched in the KRAS-high vs KRAS-low datasets in these cancers." (PMID 35563733, 2022). "In addition, the cancer region of TD3 was enriched in oxidative phosphorylation, DNA repair, E2F targets, and TNFα/NF-kB signaling." (PMID 36434043, 2022). "Collective lines of evidence suggest that DET holds the potential to induce extrinsic apoptosis by upregulating Fas/FasL, TNF/TNF-R1, DR4/5, active caspase-10, -8, -7, -3, and tBid formation in various cancer cells, which needs to be explored further using in vivo cancer models." (PMID 35408483, 2022). "Transforming growth factor beta 1 (TGF-β1), tumor necrosis factor alpha (TNF-α), and hypoxia cooperate in the triggering of EMT both in cancer and fibrosis, converging in the induction of Snail activity through different mechanisms including the activation of transcription factor NF-kB." (PMID 36291542, 2022). "Importantly, LPS sensitizes the therapeutic response of both TNBC and ER+ BC to IAP antagonist therapy by inducing the cancer cell apoptosis through toll-like receptor 4 (TLR4) and MyD88 stimulated TNFα production." (PMID 36119107, 2022). "The pathways in cancer, cytokine–cytokine receptor interaction, chemokine signaling pathway, cell-adhesion molecules (CAMs), cAMP signaling pathway, MAPK signaling pathway, and TNF signaling pathway are the significant pathways shared by the upregulated genes." (PMID 35632527, 2022). "Our results confirmed that human TNF-α and IL-6 were capable of inducing mouse myotube atrophy, indicating that the in vitro murine C2C12 myotube model can be applied for assessing cancer cachexia induced by human cancer cells." (PMID 36471329, 2022). "Thus, the decreased inflammation and induced apoptosis in these tumors suggests that in cancer, SMAC is involved in TNF-α/NF-kB signaling." (PMID 36185255, 2022). "Furthermore, cachectic patients had higher TNF-α, CCL2, and CCL3 protein expression than weight-stabilized cancer patients." (PMID 35159388, 2022). "The expression of DAPK1 decreased in cancer cells treated with TNFα and increased in cells treated with NEC-1, showing that DAPK1 may influence the progression of cancer by inhibiting necroptosis." (PMID 36505813, 2022). "Concerning this latter, include, (but are not limited to): C-X-C Motif Chemokine Receptor 1 (CXCR1) and CXCR2 (promote the recruitment of TANs to cancer); CXCL8, CXCL6 and CXCL5; Tumour Necrosis Factor alpha (TNF-α); Gamma-delta T cells (γδ T cells)-derived IL-17 (Interleukin-17)." (PMID 35406451, 2022). "Notably, UCP3 is almost exclusively expressed in skeletal muscle, and evidence suggests that cancer cachexia leads to the induction of UCP2 and UCP3 via TNF‐α." (PMID 36251564, 2022). "In clinical trials, TNF-α antibodies were not highly effective, while they were safe for use in patients with cancer." (PMID 35844550, 2022). "Survival analysis showed that CNVs of TNF in 22 cancer types, TLR3 in 10 cancer types, RIPK1 in 9 cancer types, FAS in 8 cancer types, FADD in 8 cancer types, RIPK3 in 7 cancer types, MLKL in 6 cancer types, and FASLG in 5 cancer types were significantly associated with overall prognosis." (PMID 35748782, 2022). "In contrast to soluble FasL that does not present bioactivity, both soluble TRAIL and TNF-α mediate different biological activities including killing of cancer cells." (PMID 35651603, 2022). "Moreover, the TNF‐α‐NFκB signaling and k‐RAS signaling pathways are prone to promote cancer proliferation." (PMID 34904791, 2022).
cancer (continued). "The release of the pro-inflammatory cytokines TNF-α, IL-1β and IL-8 is inhibited by 10-HDA in an in vitro model, explaining its evident effect in inhibiting tumor growth and probably inducing the anti-proliferative impact seen in other types of cancers." (PMID 36235818, 2022). "In HeLa and HepG2 cancer cells, SSD greatly increased the amount of TNF-α-mediated cell death by inhibiting TNF-α-induced NF-κB activation and the expression of its target genes, which are involved in cancer cell survival, proliferation, invasion, and angiogenesis." (PMID 36547471, 2022). "A previous research based on network pharmacology indicated that YFBD had positive effects on malignant tumors partly through PI3K and TNF pathways, which strengthened the evidence that YFBD could act on the pathways in our study." (PMID 35211182, 2022). "Cancer cell migration, invasion, and proliferation have been found to be supported by a number of proinflammatory mediators, for example, interferon-γ (IFN-γ), interleukin-6 (IL-6), and tumor necrosis factor α (TNF-α)." (PMID 36531650, 2022). "Biologic agents, particularly tumor necrosis factor (TNF)-α inhibitors, are contraindicated since they may promote the occurrence and progression of cancers." (PMID 35448208, 2022). "Polar extract of Pleurotus ostreatus effects on IL-6 and TNF-α production in treated MCF-7 cancer cells and with negative control." (PMID 35250951, 2022). "For instance, EVs derived from various cancer cell types, in addition to TGF-β, transfer tumor necrosis factor-α (TNF-α), interleukin 6 (IL-6) and matrix metalloproteinases (MMPs) to normal recipient cells, promoting their proliferation, migration and anchorage-independent growth." (PMID 35493080, 2022). "Tumor necrosis factor α (TNF-α), a pleiotropic cytokine, is one of the major elements regulating the TME and plays a vital role in inflammation, immunity, apoptosis, angiogenesis, stemness, and cancer progression." (PMID 36550571, 2022). "Such transformation favours cancer onset and progression via the TNF-α-induced release of cytokines and angiogenic factors as well as anti-apoptotic factors such as (B-cell CLL/lymphoma 2 (BCL-2)) and cyclin D1 and cyclin E in cancer cells." (PMID 35328822, 2022). "Additionally, they stimulate cancer cell growth both directly, producing EGF, IL-6 and tumor necrosis factor (TNF), and indirectly, secreting pro-angiogenic factors." (PMID 35328686, 2022). "Furthermore, previous findings are incorporated to show that TNF-α activates Wnt/β-catenin pathway, leading to increases in cancer stemness and epithelial-to-mesenchymal transition (EMT) which are involved in cancer cell renewals and tumorigenesis." (PMID 36552560, 2022). "Accordingly, the cancer cells play a key role in neutrophil infiltration into TME by producing different signals including chemokines (e.g., IL-8, CCL2, CXCL6) and cytokines (e.g., IL-1β, IL-6, TNFα)." (PMID 36330498, 2022). "An important factor promoting the migration of cancer cells is TNF-α, a pro-inflammatory cytokine that, among its many biological functions, also plays a major role in mediating the expression of MMP9, one of the key regulators of cancer cell migration." (PMID 36555705, 2022). "It is not uncommon for cancer cells to rely on a specific growth factors such as TNF alpha for viability." (PMID 35459280, 2022). "Likewise, lung cancer cell lines release factors such as TNFα and VEGF-A which enhance E-selectin expression on endothelial cells of BBB and thus increase the adhesion of cancer cells on these endothelial cells." (PMID 35884845, 2022). "TNFR2 can also be efficiently and selectively engaged using recombinant oligomeric TNFR2-specific TNF mutants, but these reagents have not been tested yet in cancer models." (PMID 35681583, 2022).